LAMA2 (laminin subunit alpha 2)
Diseases named in the same sentence as LAMA2 in open-access papers (continued):
Sharing a sentence is not in itself a finding about the gene and the disease.
Duchenne muscular dystrophy (11 papers, 2014 to 2026). Duchenne muscular dystrophy (DMD) is a neuromuscular disease characterized by rapidly progressive muscle weakness and wasting due to degeneration of skeletal, smooth and cardiac muscle. "Considering that inhibition of miR-21 expression reduced fibrosis in the mildly affected dystrophin-deficient mdx mouse model of Duchenne muscular dystrophy, we next investigated if removal of miR-21 would have propitious effects in the milder LAMA2-CMD dy2J/dy2J mouse model." (PMID 28771630, 2017). "For example, the angiotensin II type 1 receptor blocker losartan inhibits fibrosis and improves the disease in mouse models for Duchenne muscular dystrophy and LAMA2 MD." (PMID 30147969, 2018). "Taken together, our findings suggest that Thbs4 might not have the same disease-protective effect in mouse models of LGMD2E and LAMA2-RD as it was shown to have in mouse models of Duchenne muscular dystrophy and LGMD2F." (PMID 38926599, 2024). "Duchenne muscular dystrophy (DMD), Becker muscular dystrophy (BMD) and merosin-deficient congenital muscular dystrophy type 1 (MDC1A) are frequent forms caused by DMD (NM_004006.3) and LAMA2 (NM_000426.4) mutations, respectively." (PMID 41854802, 2026). "Interestingly, immunostaining for slow-twitch muscle fibers using myosin heavy chain 1A (Myh1a – F59 clone) revealed sparse detachment at the MTJ in some myotomes, similar to the early fiber detachment found in Duchenne Muscular Dystrophy (DMD) and LAMA2-related dystrophy models." (PMID 41533692, 2026). "Previous research has shown that treatment with natural Englebreth-Holm-Swam (EHS) murine sarcoma-derived laminin-111 enhances muscle regeneration and prevents myopathy of mouse models of LAMA2-CMD and Duchenne muscular dystrophy (DMD)." (PMID 32498713, 2020).
neuropathy (8 papers, 2010 to 2024). A disorder affecting the nervous system that manifests with pain, tingling, numbness, and/or muscle weakness. "However, LAMA2-RD also comprises a developmentally-associated dysmyelinating neuropathy that contributes to the disease progression, in addition to brain abnormalities; the latter often underappreciated." (PMID 32390798, 2020). "Finally, although we lack consistent data suggesting progressive axonal loss and clinically significant neuropathy in patients with LAMA2-RD, future therapies might reveal new phenotypes." (PMID 32390798, 2020). "Peripheral nerves display typical morphological features that are considered prototypic abnormalities of Lama2 neuropathy." (PMID 32390798, 2020). "Further studies will be required to evaluate whether the impaired nerve conduction might be contributing to the nuclei displacement and whether vemurafenib could be acting to improve LAMA2-CMD neuropathy in the hindlimbs of dyW−/− mice." (PMID 37021539, 2023). "In conclusion, although there is no direct evidence in human LAMA2-RD patients, data from animal models suggest that defective nerve regeneration may contribute to the progression of LAMA2 neuropathy." (PMID 32390798, 2020).
bladder cancer (7 papers, 2017 to 2023). "It has been reported that LAMA2 is not only associated with the prognosis of bladder cancer, but also strongly related to drug sensitivity." (PMID 37123010, 2023). "In this study, we first identified that the mRNA level of LAMA2 was significantly associated with the prognosis and clinical stages of bladder cancer." (PMID 37519798, 2023). "Downregulation of LAMA2 has been demonstrated in a variety of cancer types, including lung adenocarcinoma, invasive PiNETs, colon cancer, and bladder cancer, suggesting that LAMA2 is a suppressor gene." (PMID 37872487, 2023). "More importantly, seldom studies have explored the relationship between COL6A1, LAMA2, and bladder cancer, thus of great significance in our study." (PMID 36357874, 2022). "After knocking down the expression of COL6A1 and LAMA2, the Transwell assay showed that the migration ability of bladder cancer cells was down-regulated." (PMID 36357874, 2022). "And decreased expression of LAMA2 caused by promoter hypermethylation has been confirmed in various cancers, including invasive PiNETs, colon, and bladder cancers, which indicate LAMA2 is a suppressor gene." (PMID 32792503, 2020). "As a result, expression levels of CASK (p = 0.024), LAMA2 (p = 0.040), LY6D (p = 0.018), and CLDN4 (p = 0.043) were significantly associated with the overall survival of patients with urinary bladder carcinoma." (PMID 30699951, 2019). "COL6A1 and LAMA2 were again validated to promote the migration of bladder cancer cells." (PMID 36357874, 2022). "Among the remaining genes, LAMA2 (selected in 16 out of 20 folds) has been detected as a driver gene in head and neck squamous cell carcinoma and PCDH18 (selected in 11 out of 20 folds) has been detected as a driver in bladder carcinoma, cutaneous melanoma and in a pan-cancer analysis setting." (PMID 28650955, 2017). "However, the role of LAMA2 in bladder cancer has not been investigated." (PMID 37519798, 2023).
cardiomyopathy (7 papers, 2010 to 2022). A disease of the heart muscle or myocardium proper. "Missense mutations or small deletions in some genes, for example, desmin (Des), integrin-linked protein kinase (Ilk), myosin regulatory light chain 2 (My12), dystrophin (Dmd), gelsolin (Gsn), lamin A/C (Lmna), and laminin subunit α-2 (Lama2), have been linked to cardiomyopathy." (PMID 23671862, 2013). "Eight (11.59%) hits concerned substrate defects, such as fibro-adipose substitution or RV end-diastolic volume (EDV), and they mainly involved genes associated with cardiomyopathies and muscle dysfunction, including TRIM63, MYH6, SGCD and LAMA2." (PMID 36008935, 2022). "TTN, GAA, LAMA2, and MYBPC3 contained the most variants in the three subgroups which confirm the impact of these genes in the complex pathogenesis of cardiomyopathies and VT." (PMID 33552729, 2021). "TTN, GAA, LAMA2 and MYBPC3 harbored the most variants in the three subgroups which confirm the high impact of these genes in complex pathogenesis of cardiomyopathies and VT demonstrated in previous studies." (PMID 33552729, 2021). "Integrin family genes and LAMA2 were selected primarily within high-ranking cardiomyopathy, focal adhesion and ECM receptor signaling pathways, with once again the dilated cardiomyopathy pathway achieving the highest ranks." (PMID 24278029, 2013). "Studies have demonstrated that homozygous mutation of LAMA2 can cause unstable myotube formation in various cardiac muscle, and abnormal LAMA2 expression may lead to heart dieases, such as cardiomyopathy, heart failure, and dilated cardiomyopathy." (PMID 35207515, 2022).
epilepsy (7 papers, 2017 to 2025). A brain disorder characterized by episodes of abnormally increased neuronal discharge resulting in transient episodes of sensory or motor neurological dysfunction, or psychic dysfunction. "Another report described five patients with LAMA2 mutations, of which two patients had epilepsy and three patients had more subtle neurological symptoms." (PMID 32792907, 2020). "LAMA2-related congenital muscular dystrophy (LAMA2-MD) is a genetically heterogeneous disorder defined by progressive muscle weakness, brain structural abnormalities, epilepsy, and multisystem involvement." (PMID 41567540, 2025). "The patient had clinical manifestations of LGMD R23, such as increased CK levels, epilepsy, typical widespread abnormal white matter hyperintensities on T2-MRI found in LAMA2-MD, and peripheral neuropathy." (PMID 37206914, 2023). "In LAMA2-CMD, survival was related to head control (p = 0.022) and sitting ability (p = 0.010), and epilepsy was associated with lower rate of survival (p = 0.015)." (PMID 34281576, 2021). "In a Spanish cohort, it was found that the extension of polymicrogyria in LAMA2-RD may serve as a predictor of epilepsy occurrence." (PMID 37206914, 2023). "Seizures occurred in 9.5% (11/116) of LAMA2-CMD patients (night with epilepsy and two with febrile seizures) and 35.7% (5/14) of LGMDR23 patients (three with epilepsy and two with febrile seizures)." (PMID 34281576, 2021).
lung adenocarcinoma (7 papers, 2014 to 2025). A carcinoma that arises from the lung and is characterized by the presence of malignant glandular epithelial cells. "We also found that LAMA2 is frequently mutated in other cancers, including lung adenocarcinoma (11%), lung squamous cell carcinoma (13%), uterine corpus endometrioid carcinoma (13%), and head and neck squamous cell carcinoma (10%) (data source: The Cancer Genome Atlas)." (PMID 25159915, 2014). "Separately, LAMA2 expression inhibits lung adenocarcinoma metastasis, such that destabilizing LAMA2 mRNA through Mex3a binding promotes lung adenocarcinoma cell migration and invasion." (PMID 34982945, 2022). "Interestingly, it has been shown that the down-regulation of LAMA2 promoted migration and invasion in lung adenocarcinoma." (PMID 39811640, 2025). "However, the role of LAMA2 in lung adenocarcinoma remains unknown." (PMID 32792503, 2020). "Our results show that Lama2 have a negative effect on the proliferation of hippocampal NSCs, keeping consistency with its roles in the malignant progression of lung adenocarcinoma, pituitary adenoma, hepatocellular carcinoma, and colorectal cancer." (PMID 37091532, 2023).
colorectal cancer (6 papers, 2014 to 2023). A primary or metastatic malignant neoplasm that affects the colon or rectum. "uncovered that the methylation level of LAMA2 had a crucial role in the onset and advancement of colorectal cancer." (PMID 36518255, 2022). "Downregulation of Lama2 expression was also found, notably in liver, ovarian, lung, and colorectal cancer." (PMID 34305583, 2021). "Down regulation and mutations in ROBO2 have been reported in prostate, gastric and colorectal cancers; while LAMA2 down regulation has been reported in drug-resistant ovarian cancer cell lines." (PMID 26620706, 2015). "We examined a comprehensive panel of tumor tissues for expression profiling, and found downregulation of LAMA2 across multiple cancer types, most notably in ovarian, lung and colorectal cancer." (PMID 25159915, 2014).
dystroglycanopathies (6 papers, 2019 to 2024). "The most common forms are dystroglycanopathies (DGP; 12–25%), Collagen 6 related disorders (COL6-RD) (12–19%), laminin-alpha 2 related dystrophies (LAMA2-RD; 10–37%), and selenoprotein N related myopathy (SEPN1-RM; 11.65%)." (PMID 38678519, 2024).
myopia (6 papers, 2013 to 2023). "Early genome-wide association study on myopia in Europeans has revealed that LAMA2, a gene involved in the extracellular matrix, associated with the mechanism behind the development of myopia." (PMID 36313450, 2022). "These vQTLs are strong candidates for having either GxE or GxG interaction effects and, indeed, genetic variants located near the GJD2, LAMA2, RBFOX1, KCNQ5 and LRRC4C genes were associated with a progressively increasing risk of myopia as the number of years of schooling rose." (PMID 36395078, 2022). "Hence, the current approach of testing for non-additive effects provides further evidence, albeit circumstantial, linking the 3 variants to specific genes likely to have causal roles in myopia: ZMAT4, RD3L and LAMA2." (PMID 32227305, 2020). "We found a significantly increased axial length and myopic shift in refractive status in three of our studied mutants, indicating a potential involvement of the human orthologs (LAMA2, LRRC4C, and KCNQ5) in myopia development." (PMID 36737489, 2023).
Respiratory insufficiency (6 papers, 2013 to 2023). "Research in the LAMA2-RDs has benefited from the availability of multiple mouse models which, to varying degrees, recapitulate the human clinical phenotype of skeletal muscle weakness, respiratory insufficiency, and neuropathy." (PMID 32848593, 2020).
hepatocellular carcinoma (5 papers, 2014 to 2023). A malignant tumor that arises from hepatocytes. "LAMA2 has also been implicated in a number of other cancers and mutations in this gene have been identified in 14% of hepatocellular carcinomas and aberrant methylation in 80% of colorectal cancers." (PMID 30575736, 2018). "Therefore, the LAMA2-deficient samples represent a subgroup of highly recurrent and proliferative hepatocellular carcinomas, and LAMA2-based stratification appears to apply to other cancer types as well." (PMID 25159915, 2014).
dilated cardiomyopathy (4 papers, 2013 to 2023). Cardiomyopathy which is characterized by dilation and contractile dysfunction of the left and right ventricles. "Dilated cardiomyopathy (DCM) pathway, including Lama2, Tnnt2, Actg1, Atp2a2, Gnas, Tpm3, Itga6, Tpm1, and Pln, was enriched in the KEGG pathway." (PMID 37858115, 2023).
ependymoma (4 papers, 2016 to 2023). A WHO grade II, slow growing tumor of children and young adults, usually located intraventricularly. "Single transcriptome analyses indicated the linked to a worse prognosis upregulation of LAMA2 in PFA ependymomas." (PMID 27390862, 2016). "LAMA2 (Laminin alpha-2) expression has been suggested as a surrogate marker for PF Group A ependymomas." (PMID 27550150, 2016). "The aim of this study was to analyze the status of chromosome 1q, TNC, LAMA2, and NELL2 expression in a series of pediatric PF ependymomas in terms of their frequency, associations among themselves and clinical parameters, as well as their prognostic impact." (PMID 27550150, 2016). "In a previously analyzed cohort of PF ependymomas LAMA2 was expressed in 67 % of the tumors in patients ≤ 21 years, thus in a similar percentage, however 10 % of these patients expressed also NELL2." (PMID 27550150, 2016). "LAMA2 has recently been identified as a molecular marker of aggressive ependymoma, and a promoter of malignancy in glioblastomas (GBMs) through the maintenance of GBM stem cell compartment; therefore, it can be used as a molecular fingerprint and a possible therapeutic target for GBMs." (PMID 37519798, 2023). "Therefore, we have analyzed the status of chromosome 1q, TNC, LAMA2, and NELL2 expression in a series of pediatric PF ependymomas in terms of their frequency, associations among themselves, and clinical parameters, as well as their prognostic impact." (PMID 27550150, 2016). "In our analysis average dCt values for LAMA2 and NELL2 genes expression were higher in grade III ependymomas what indicated that more aggressive tumors showed lower expression values." (PMID 27390862, 2016).
Lissencephaly (4 papers, 2019 to 2025). A spectrum of malformations of cortical development caused by insufficient neuronal migration that subsumes the terms agyria, pachygyria and subcortical band heterotopia. "Recently, cortical malformations, including polymicrogyria, lissencephaly-pachygyria, and cobblestone, most severe in the occipital lobe, such as occipital pachygyria, have been thought to be an important manifestation of the brain pathology in LAMA2-MD." (PMID 40960171, 2025).
muscle disorder (4 papers, 2017 to 2022). "Although LAMA2 is mainly related to muscular diseases (see editorial 70), some authors have indicated functions in immune response." (PMID 36443886, 2022).
Seizure (4 papers, 2019 to 2025). A seizure is an intermittent abnormality of nervous system physiology characterized by a transient occurrence of signs and/or symptoms due to abnormal excessive or synchronous neuronal activity in the brain. "Seizures have been thought as a main symptom of brain dysfunctions in LAMA2-MD, which might be associated with cortical malformation." (PMID 40960171, 2025). "Seizures were reported in 8–50% of LAMA2-CMD, while were found in 35.7% of LGMDR23 and 9.5% of LAMA2-CMD patients in this study." (PMID 34281576, 2021). "Seizures were more frequent in LGMDR23 (35.7%) than in LAMA2-CMD (9.5%)." (PMID 34281576, 2021). "Seizures occurred in 35.7% of LGMDR23 and 9.5% of LAMA2-CMD patients." (PMID 34281576, 2021).
Bethlem myopathy (3 papers, 2020 to 2022). A usually autosomal dominant inherited movement disorder caused by mutations in the COL6A1, COL6A2, and COL6A3 genes. "Similar to LAMA2-related diseases, collagen VI-related myopathies show a continuum of phenotypes ranging from comparably mild Bethlem myopathy to severe Ullrich congenital muscular dystrophy." (PMID 36523505, 2022).
glioblastoma (3 papers, 2020 to 2025). The most malignant astrocytic tumor (WHO grade IV). "However, recent study have revealed opposite effects of LAMA2 as an oncoprotein in glioblastoma and ependymoma." (PMID 32792503, 2020).
glioma (3 papers, 2016 to 2025). A benign or malignant brain and spinal cord tumor that arises from glial cells (astrocytes, oligodendrocytes, ependymal cells). "Unfortunately, there are limited studies concerning the role of LAMA2 in brain tumors, although it has been postulated that this is an element of the differentiation niche of glioma initiating cells and considered responsible for therapeutic resistance and the recurrence of a subset of glial tumors." (PMID 27390862, 2016). "In pediatric gliomas, while LGAT was found to overexpress S1PR3 to a slightly greater degree than HGAT, LGAT had comparatively lower overexpression of LAMA2 than that of HGAT." (PMID 40227800, 2025).
lung carcinoma (3 papers, 2014 to 2023). "LAMA2 is a suggested tumor suppressor and is frequently mutated in other cancers, such as lung cancers." (PMID 31805664, 2019). "Interestingly, high expression of DCN, LAMA2, and ELN in lung cancer is associated with better survival." (PMID 37848457, 2023).
Marfan syndrome (3 papers, 2018 to 2025). A disorder of the connective tissue. "Recently orphan drug Tarix (TXA127), which counteracts the classical renin angiotensin system, was announced and approved by FDA for LAMA2 MD, Marfan Syndrome, and amyotrophic lateral sclerosis (ALS)." (PMID 30147969, 2018).
schizophrenia (3 papers, 2017 to 2023). A major psychotic disorder characterized by abnormalities in the perception or expression of reality. "Among them, SNAPIN physically interacts with LAMA2 and is implicated in the pathophysiology of schizophrenia." (PMID 37511534, 2023). "In family 1, with singleton schizophrenia, we detected four rare variants in genes implicated in schizophrenia, including p.Arg1627Trp of LAMA2, p.Pro1338Ser of CSMD1, p.Arg691Gly of TLR4, and Arg182X of AGTR2." (PMID 37511534, 2023). "A genetic study of schizophrenia discovered that recurrent de novo mutations of LAMA2 were found significantly more often in schizophrenia than controls, suggesting that LAMA2 variants may be involved in neuropsychiatric disorders." (PMID 37511534, 2023). "Intriguingly, several schizophrenia-associated genes such as NRXN1 and LAMA2 also contain LamG domains." (PMID 29302076, 2019). "For instance, neurons from schizophrenia patients with mutated DISC1, which is thought to have a neurodevelopmental dimension to its pathology, show downregulation of metabolic pathways and LAMA2, a gene in which de novo mutations have been identified in cases of sporadic schizophrenia." (PMID 29051230, 2017).
scoliosis (3 papers, 2018 to 2024). A congenital or acquired spinal deformity characterized by lateral curvature of the spine. "Scoliosis occurred in 40.5% (45/111) of LAMA2-CMD at median age of 6.0 years (range 0.5–12.0 years), and lordosis occurred in 8.1% (9/111) of LAMA2-CMD at median age of 3.0 years (range 2.0–7.0 years)." (PMID 34281576, 2021). "Counting of scoliosis-related genes indicated that NF1, FBN1, LAMA2 and SPG11 led the top list of genes concerned with scoliosis." (PMID 39502335, 2024).